ARHGAP15 (Rho GTPase activating protein 15)
Description:
GTPase activator for the Rho-type GTPases by converting them to an inactive GDP-bound state. Has activity toward RAC1. Overexpression results in an increase in actin stress fibers and cell contraction.
Synonyms: BM046
Tractability: Small molecule: it has a high-quality binding pocket. Antibody: UniProt places it where antibodies can reach, with high confidence; its Gene Ontology location is reachable by antibodies, with high confidence; the Human Protein Atlas places it where antibodies can reach. PROTAC: ubiquitination databases record sites on it; its protein half-life has been measured.
Gene: Protein-coding gene on chromosome 2 (143,091,362 to 143,768,352, forward strand). Ensembl gene ENSG00000075884.
Subcellular location: Cytoplasm; Membrane
Subcellular location (Human Protein Atlas): Plasma membrane
Pathways (Reactome):
Signal Transduction: RAC1 GTPase cycle; RAC3 GTPase cycle
Gene Ontology:
Molecular function: GTPase activator activity; protein binding
Biological process: regulation of cell shape; regulation of small GTPase mediated signal transduction; small GTPase-mediated signal transduction; signal transduction
Cellular component: plasma membrane; cytoplasm; cytosol; membrane
Genetic constraint (gnomAD): Loss-of-function variants: 34 observed, 39.91 expected, observed/expected ratio (o/e) 0.85, 90% interval 0.65 to 1.13. The upper end of that interval is the gene's LOEUF score, 1.13, which puts it in group 4 of 6, group 1 being the genes least tolerant of losing a copy. Missense variants: 458 observed, 475.05 expected, observed/expected ratio (o/e) 0.96, 90% interval 0.89 to 1.04. Synonymous variants: 160 observed, 166.61 expected, observed/expected ratio (o/e) 0.96, 90% interval 0.84 to 1.1.
Homologues: Orthologues: chimpanzee ARHGAP15 (99% identical), macaque ARHGAP15 (99% identical), dog ARHGAP15 (95% identical), rabbit ARHGAP15 (94% identical), guinea pig ARHGAP15 (94% identical), pig ARHGAP15 (87% identical), mouse Arhgap15 (86% identical), rat Arhgap15 (84% identical), tropical clawed frog ARHGAP15 (62% identical), zebrafish arhgap15 (57% identical), Caenorhabditis elegans tag-325 (30% identical), Drosophila melanogaster RhoGAP16F (22% identical). Paralogues in human: ARHGAP12 (45% identical), ARHGAP27 (41% identical), ARHGAP9 (39% identical).
Diseases named in the same sentence as ARHGAP15 in open-access papers:
ARHGAP15 is named in the same sentence as 43 diseases in open-access papers, as found by Europe PMC text mining. Sharing a sentence is not in itself a finding about the gene and the disease. The quoted sentences say what the papers report.
cognitive deficits (7 papers, 2016 to 2022). "In human, loss of ArhGAP15 has been associated to cognitive disorders, in the Mowat-Wilson disease, characterized by severe neurological and cognitive deficits, severe ID and speech impairment, and in most cases epilepsy." (PMID 29740022, 2018). "In mice loss of ArhGAP15 results in increased Rac1/Rac3 activity, reduced spine density, reduced axonal and dendritic complexity and cognitive deficits." (PMID 29925821, 2018). "Loss of ARHGAP15 has been documented in a rare variant of the Mowat-Wilson disease, which is characterized by severe neurological and cognitive deficits, autism and speech impairments." (PMID 29925821, 2018). "A loss of ARHGAP15 gene function has been reported in patients with a rare genetic mutation in Mowat‐Wilson disease, which is characterized by several phenotypes, including autism and speech impairment, and severe neurological and cognitive deficits." (PMID 32431071, 2020). "Functionally, ArhGAP15−/− mice exhibit decreased synaptic density, altered electroencephalographic rhythms and cognitive deficits." (PMID 29740022, 2018). "Functionally, ArhGAP15−/− mice exhibit altered electroencephalographic rhythms and cognitive deficits." (PMID 29740022, 2018). "In the absence of ArhGAP15 we also noticed a reduced number of CR+ neurons, thus the cognitive deficits of ArhGAP15−/− animals are likely to result from the combined impairment of both PV+ and CR+ neuron subtypes." (PMID 27713499, 2016). "These are associated with a variety of neurological diseases, such as cognitive defects (ARHGAP15), migraine without aura (ARHGAP28), AD (ARHGAP2), schizophrenia (ARHGAP18), and bipolar disorder (BD; ARHGAP29; Niftullayev and Lamarche-Vane, 2019)." (PMID 35783123, 2022).
glioma (5 papers, 2018 to 2025). A benign or malignant brain and spinal cord tumor that arises from glial cells (astrocytes, oligodendrocytes, ependymal cells). "Abnormal expression of ARHGAP15 has been reported in human gliomas, where it is associated with more aggressive tumor phenotypes." (PMID 41373823, 2025). "Remarkably, studies have shown that FOXP3 can regulate the expression of ARHGAP15 in glioma, with significant correlations between ARHGAP15 expression and glioma severity." (PMID 39075640, 2024). "On the other hand, the importance of ARHGAP15 in the progression of human gliomas has been also reported." (PMID 29534468, 2018). "On the other hand, ARHGAP15 is reported to be regulated by transcription factor forkhead box P3 (FOXP3) in glioma cells." (PMID 29534468, 2018). "Recently, ARHGAP15 has been reported to be expressed in human gliomas and to suppress migration and invasion of U87 and U251 human glioma cells." (PMID 29534468, 2018). "For example, ARHGAP15 decreased in glioma, which promoted the aggressive phenotypes of glioma cells through the activation of Rac19." (PMID 29867200, 2018). "Interestingly, ARHGAP15 has been reported as a tumor suppressor in all published studies, such as lung cancer, breast cancer, colon cancer and glioma, which is contradictory to our findings." (PMID 36802400, 2023). "Indeed, all previously published studies supported the notion by demonstrating that ARHGAP15 functioned as a tumor suppressor in lung cancer, breast cancer, colon cancer and glioma." (PMID 36802400, 2023). "The downregulation of Rho GTPase-activating protein 15 (ARHGAP15), a Rac1-specific GAP, has been observed in glioma and pancreatic ductal adenocarcinoma." (PMID 29867200, 2018).
breast carcinoma (4 papers, 2018 to 2025). "In contrast, another study found that ARHGAP15 immunoreactivity correlated with improved prognosis and a lower risk of recurrence in breast carcinoma tissues, possibly through Rac1 inactivation." (PMID 41373823, 2025). "Our study demonstrated that ARHGAP15 immunoreactivity was significantly associated with decreased risk of recurrence and better prognosis in breast carcinoma patients." (PMID 29534468, 2018). "In the present study, ARHGAP15 immunoreactivity was detected in 47% of breast carcinoma cases, and was significantly associated with that of Rac1, while it was almost negligible in morphologically normal mammary epithelium." (PMID 29534468, 2018). "In order to address the prognostic implications of ARHGAP15 and Rac1 in human breast carcinoma patients, we associated the immunoreactivity of them with the clinical outcome of the patients." (PMID 29534468, 2018). "ARHGAP15 is shown to be related to better prognosis of early stage pancreatic cancer and breast cancer." (PMID 35433680, 2022). "ARHGAP15 immunoreactivity is therefore considered a potent prognostic factor in human breast carcinomas." (PMID 29534468, 2018). "In order to examine the effects of ARHGAP15 on breast cancer progression, we performed cell proliferation assay and migration assay." (PMID 29534468, 2018). "ARHGAP15 is therefore considered to suppress migration of breast carcinoma cells by inactivating Rac1." (PMID 29534468, 2018). "In our previous study, we pointed out that expression of ARHGAP15 mRNA is possibly regulated by androgens in breast cancer cells after results found using microarray analysis." (PMID 29534468, 2018). "Therefore, we examined the significance of ARHGAP15 using immunohistochemistry and explored the effects of ARHGAP15 on breast cancer cell proliferation and migration." (PMID 29534468, 2018). "Although a lot of studies have pointed out the pivotal roles of the Rac1 pathway in the progression of breast carcinomas, the clinical significance of ARHGAP15 has remained largely unknown in human breast carcinomas." (PMID 29534468, 2018). "Further examinations with a larger number of samples may be needed in order to clarify more precisely the roles of ARHGAP15 in breast cancer cell proliferation." (PMID 29534468, 2018). "It was therefore reasonably considered that ARHGAP15 may suppress the progress of breast carcinomas by attenuating the Rac1 pathway and may serve as better prognostic factor in breast carcinomas." (PMID 29534468, 2018). "Considering that ARHGAP15 suppresses breast cancer cell proliferation and migration it may be possible to speculate that anti-tumorigenic effects of androgens are partially due to the induction of ARHGAP15 and subsequent inactivation of Rac1." (PMID 29534468, 2018). "Therefore, we immunolocalized ARHGAP15 in one hundred breast carcinoma tissues." (PMID 29534468, 2018). "Therefore, it is suggested that ARHGAP15 may be expressed and have pivotal roles in the progress of human malignancies including breast carcinomas, affecting the Rac1 pathway." (PMID 29534468, 2018). "Therefore, ARHGAP15 is considered an androgen-induced gene in human breast carcinomas." (PMID 29534468, 2018). "In summary, we immunolocalized ARHGAP15 and Rac GAP in human breast carcinoma tissues, and ARHGAP15 immunoreactivity was significantly correlated with AR LI, decreased risk of recurrence, and better prognosis for the patients." (PMID 29534468, 2018). "Expression of ARHGAP15 is therefore considered to be regulated by several mechanisms other than androgens, such as FOXP3, in breast carcinomas." (PMID 29534468, 2018). "However, ARHGAP15 and its regulation have not been examined in breast carcinomas." (PMID 29534468, 2018).
diverticular disease (4 papers, 2017 to 2023). A complex disorder characterised by mucosal outpouchings (diverticulae) of the colonic wall which can become infected and inflamed leading to diverticulitis, perforation and bleeding. "Our multi-ancestry GWAS of DD confirmed the strong genome-wide association of ARHGAP15 with both diverticulosis and diverticulitis." (PMID 37196047, 2023). "The data on the risk variant rs4662344 in ARHGAP15 was less consistent, it was borderline significantly associated with both diverticulosis and diverticulitis, but for confirmation additional larger studies are warranted." (PMID 32015353, 2020). "The major (T) allele of rs4662344 in ARHGAP15 was significantly (OR 1.28; 95% CI 1.00–1.63) associated with diverticulosis." (PMID 32015353, 2020). "We tested the association of diverticulitis versus uncomplicated diverticular disease for variants at the ARHGAP15, COLQ and FAM155A loci." (PMID 28585551, 2017). "Ancestry-stratified analyses of diverticulosis and diverticulitis of the identified subjects replicated the well-established associations between ARHGAP15 loci with DD, showing overall intensified GWAS signals in diverticulitis patients compared to diverticulosis patients." (PMID 37196047, 2023). "We have found common sequence variants in introns of the ARHGAP15, COLQ and FAM155A that associate with risk of diverticular disease or diverticulitis." (PMID 28585551, 2017). "The minor allele of the variant rs4662344 in ARHGAP15 was more frequent in diverticulitis cases in comparison to controls with diverticulosis and no prior diverticulitis, as similarly described previously in the GWAS10,12,13." (PMID 32015353, 2020). "Despite the role of Rho GTPase-activating protein 15, encoded by ARHGAP15, on phagocyte function and inflammation the ARHGAP15 variant associating with diverticular disease does not affect ROS production by neutrophils." (PMID 28585551, 2017). "None of the three missense variants in ARHGAP15 (15 exons 475 amino acids) associate with diverticular disease (P>0.44)." (PMID 28585551, 2017). "The strongest diverticular disease association in Iceland was with 45 correlated (r2>0.97) sequence variants (minor allele frequency (MAF)=17.6–17.8%) in 88 kb region spanning introns 9 and 10 of ARHGAP15 (Rho GTPase-activating protein 15)." (PMID 28585551, 2017). "We find association of three intronic variants in the genes ARHGAP15 (Rho GTPase-activating protein 15) and COLQ (collagen-like tail subunit of asymmetric acetylcholinesterase) with diverticular disease and in FAM155A (family with sequence similarity 155A) with diverticulitis." (PMID 28585551, 2017). "Our results indicate, that the variant in FAM155A is associated with diverticulitis, but not diverticulosis in Caucasians, whereas a risk variant in ARHGAP15 might be associated with both diverticulosis and diverticulitis." (PMID 32015353, 2020).
diverticulitis (4 papers, 2017 to 2024). An infection that develops in the diverticula of the intestinal tract. "The variant rs4662344 in ARHGAP15 was borderline significantly (OR 1.43; 95% CI 1.00–2.03; P = 0.05) associated with diverticulitis after adjusting for the corresponding cofactors." (PMID 32015353, 2020). "GWAS on the Icelandic, Denmark and UK populations replicated gene variants in ARHGAP15, COLQ and FAM155A with increased association with diverticulitis over diverticulosis." (PMID 38831715, 2024). "We performed additional GWASs in the ICD-phenotyped diverticulitis cohort and replicated an ARHGAP15 locus on chromosome 2 (rs6717024) as genome-wide significant." (PMID 37196047, 2023). "Four replicated loci, ARHGAP15, COLQ, FAM155A and TNFSF15, are highlighted to have a stronger association with diverticulitis and may have a role in inflammation." (PMID 38831715, 2024). "Even though ARHGAP15 loci showed non-significant p-values of 0.24–0.99 in the AA GWAS, the effect directions of ARHGAP15 loci were mostly positive and substantial, ranging from 1.111 to 1.464 in AA diverticulitis GWAS, except few loci which showed negative ORs." (PMID 37196047, 2023).
schizophrenia (4 papers, 2020 to 2025). A major psychotic disorder characterized by abnormalities in the perception or expression of reality. "Seven switch genes, NPAS3, ARHGAP15, LGALS3BP, DPP10, SMYD3, CPXCR1, and HLA-DRB5 were associated with known risk factors for schizophrenia." (PMID 36982982, 2023). "Likewise, NPAS3, ARHGAP15, LGALS3BP, DPP10, SMYD3, CPXCR1, and HLA-DRB5 were associated with known risk factors for schizophrenia." (PMID 36982982, 2023).
asthma (2 papers, 2022). "However, several genes are newly implicated in asthma, including Rho GTPase activating protein 15 (Arhgap15), Pleckstrin (Plek), and Transcription factor EC (Tfec)." (PMID 35600600, 2022). "Furthermore, the immunomodulatory genes TNFAIP8 and ARHGAP15 were identified in GWAS studies as shared risk variants for several IgE-mediated diseases including asthma, allergic rhinitis and atopic eczema." (PMID 36106020, 2022). "Arhgap15 has been called a ‘‘master negative regulator of neutrophil functions’’, and validated as a differentially expressed novel transcript in patients with asthma." (PMID 35600600, 2022).
colorectal cancer (2 papers, 2018 to 2025). A primary or metastatic malignant neoplasm that affects the colon or rectum. "A decreased level of ARHGAP15 expression promotes the development of colorectal cancer via the PTEN/AKT/FOXO1 axis." (PMID 39833662, 2025).
gastric cancer (2 papers, 2023 to 2025). A primary or metastatic malignant neoplasm involving the stomach. "It has been reported that Rho GTPase-activating protein 15 (ARHGAP15) is highly expressed in gastric cancer to promote the colonization and metastasis of gastric cancer cells." (PMID 40227215, 2025). "Taken together, these findings suggested a novel role of ARHGAP15 in promoting gastric cancer metastasis by quenching ROS through inhibiting RAC1 and its potential value for prognosis estimation and targeted therapy." (PMID 36802400, 2023). "In conclusion, we demonstrated ARHGAP15 promoted metastatic colonization by enhancing the antioxidant capacity of gastric cancer cells in a RAC1 dependent way." (PMID 36802400, 2023). "Ectopic expression of ARHGAP15 promoted metastatic colonization of gastric cancer cells in murine lungs and lymph nodes in vivo or protected cells from oxidative-related death in vitro." (PMID 36802400, 2023). "Therefore, we proceeded to investigate the exact role of ARHGAP15 in gastric cancer metastasis to see if it was a “double-edged sword” under different circumstances." (PMID 36802400, 2023). "With the functional study in vivo and in vitro, we demonstrated that ARHGAP15 could promote gastric cancer metastatic colonization." (PMID 36802400, 2023). "However, our recent findings suggested ARHGAP15 as a pro-metastasis gene in gastric cancer, which was inconsistent with its phenotype shown in previous studies." (PMID 36802400, 2023). "Here we reported that ARHGAP15, a Rho GTPase activating protein, enhanced gastric cancer (GC) metastatic colonization, which was quite different from its reported role as a tumor suppressor gene in other cancers." (PMID 36802400, 2023).
Intellectual disability (2 papers, 2021 to 2022). "Loss of ARHGAP15 has been reported in one case of severe intellectual disability and a rare variant of Mowat–Wilson syndrome, a disease characterized by epilepsy." (PMID 36568982, 2022).
pancreatic ductal adenocarcinoma (2 papers, 2018 to 2019). An infiltrating adenocarcinoma that arises from the epithelial cells of the pancreas. "ARHGAP15 is correlated with survival in early-stage pancreatic ductal adenocarcinoma." (PMID 30704450, 2019).
giant cell arteritis (1 paper, 2025). "DDIT4 and ARHGAP15 have significant causal effects on giant cell arteritis risk." (PMID 39762453, 2025).
Mowat-Wilson syndrome (1 paper, 2018). Mowat-Wilson syndrome (MWS) is a multiple congenital anomaly syndrome characterized by a distinct facial phenotype, intellectual disability, epilepsy, Hirschsprung disease (HSCR) and variable congenital malformations. "In the most severe variants of the Mowat-Wilson syndrome, the loss of ArhGAP15 accompanies the deletion of Zeb2, the known disease gene." (PMID 29740022, 2018).
Paralytic ileus (1 paper, 2023). "Our PheWAS of the independent ARHGAP15 loci (rs6736741, rs10928187, rs386651361) confirmed its significant phenotypic expression with DD in MA and EA and the second most significant association with paralytic ileus." (PMID 37196047, 2023).
Sepsis (1 paper, 2022). Sepsis is defined as life-threatening organ dysfunction caused by a dysregulated host response to infection. "In an in vivo sepsis model, lack of ArhGAP15 (Rho GTPase-activating protein 15), which functions as a negative regulator of multiple neutrophil functions, induced cellular elongation but resulted in more efficient neutrophil migration, phagocytosis, and bacterial killing." (PMID 35173190, 2022).